TRPM1 (transient receptor potential cation channel subfamily M member 1)
Diseases named in the same sentence as TRPM1 in open-access papers (continued):
Sharing a sentence is not in itself a finding about the gene and the disease.
Nystagmus (3 papers, 2021 to 2024). Rhythmic, involuntary oscillations of one or both eyes related to abnormality in fixation, conjugate gaze, or vestibular mechanisms. "Those with the GRM6, TRPM1, or CACNA1F variants had both amblyopia and nystagmus." (PMID 36499293, 2022).
Paraneoplastic Retinopathy (3 papers, 2011 to 2013). "A greater understanding of why TRPM1 autoantibodies do not cross the ILM of the rodent may provide a path to designing treatments for autoimmune and paraneoplastic retinopathies." (PMID 23936334, 2013).
retinal dystrophies (3 papers, 2011 to 2024). "Furthermore, 24 families had VUS, two families with variants in genes related to non-syndromic EoHM (SCO2 and ZNF644) and seven families with variants in genes associated with other retinal dystrophies (TRPM1, CACNA1F, KCNV2, RDH5 and MERTK)." (PMID 35457050, 2022).
retinitis pigmentosa (3 papers, 2019 to 2025). Retinitis pigmentosa (RP) is an inherited retinal dystrophy leading to progressive loss of the photoreceptors and retinal pigment epithelium and resulting in blindness usually after several decades. "The rd1 retina, a model for retinitis pigmentosa with severe photoreceptor degeneration, displays similar oscillations to the Trpm1 KO retina." (PMID 41099728, 2025).
Anxiety (2 papers, 2021 to 2022). Intense feelings of nervousness, tension, or panic often arise in response to interpersonal stresses. "Our data revealed abnormal behaviors in Trpm1-deficient mice, including reduced anxiety-like behavior, abnormal social interactions, attenuated fear and spatial memories, and the most prominent phenotype of Trpm1 mutant mice, hyperlocomotor activity." (PMID 33785025, 2021). "The lack of a significant reduction of corticosterone, which is related to anxiety-like behavior, suggests that the hyperactivity observed in Trpm1−/− mice simulates reduced anxiety in our tests, and underlies or contributes to other phenotypes of Trpm1−/− mice." (PMID 33785025, 2021). "In the light/dark transition test, distance traveled in the light and dark chamber was significantly increased in Trpm1−/− mice, suggesting reduced anxiety-like behavior." (PMID 33785025, 2021). "Our data demonstrate that Trpm1−/− mice exhibit abnormal behaviors that may explain some phenotypes of 15q13.3 microdeletion syndrome, including reduced anxiety-like behavior, abnormal social interaction, attenuated fear memory, and the most prominent phenotype of Trpm1 mutant mice, hyperactivity." (PMID 33785025, 2021).
autosomal recessive congenital stationary night blindness (2 papers, 2019 to 2023). "Although TRPM1 encodes a calcium-permeable cation channel, which has been associated with autosomal recessive congenital stationary night blindness (CSNB), a case has recently been described in a 4-week-old boy of non-consanguineous parents affected by unilateral nuclear cataracts." (PMID 37511188, 2023).
cutaneous melanoma (2 papers, 2012 to 2017). A primary melanoma arising from atypical melanocytes in the skin. "TRPM1 (melastatin) expression loss occurred at the transition of radial to vertical growth primary cutaneous melanoma." (PMID 28278159, 2017). "TRPM1 was initially identified in melanocytes and cutaneous melanoma and is a marker for metastasis and prognosis." (PMID 23148706, 2012).
lung carcinoma (2 papers, 2011 to 2018). "In the current study, we identified autoantibodies against the transient receptor potential cation channel, subfamily M, member 1 (TRPM1) in the serum of one patient with lung cancer." (PMID 21611200, 2011).
metastatic melanoma (2 papers, 2015 to 2017). A melanoma that has spread from its primary site to another anatomic site. "miR-211 induction was confirmed in vivo by analyzing TRPM1 levels in tumor biopsies obtained from patients with metastatic melanoma who eventually progressed on treatment with BRAFi and/or MEKi." (PMID 28445987, 2017). "In line with this, it has been suggested that the levels of TRPM1 mRNA can be used to predict the future development of metastatic melanoma." (PMID 25710007, 2015). "In contrast to TRPM1, TRPM7 is highly expressed in metastatic melanoma." (PMID 25710007, 2015).
Spitz nevi (2 papers, 2012 to 2023). "The patterns of TRPM1 transcript expression also help differentiate Spitz nevi from nodular melanomas, with higher ubiquitous expression in Spitz nevi and higher incidence of loss in nodular melanomas." (PMID 23148706, 2012).
autism (1 paper, 2021). Persistent deficits in social interaction and communication and interaction as well as a markedly restricted repertoire of activity and interest as well as repetitive patterns of behavior. "Relevant to the effect of MPH in Shank2- and Fmr1-deficient mice, hyperactivity of Trpm1-deficient mice may not be related to ADHD, but instead autism which is also one of the phenotypes of 15q13.3 microdeletion syndrome." (PMID 33785025, 2021).
cataract (1 paper, 2023). Partial or complete opacity of the crystalline lens of one or both eyes that decreases visual acuity and eventually results in blindness. "In reference to family OFT-00334, the female proband presented bilateral cataracts and was heterozygous for the mutation in the TRPM1 (OMIM 603576) gene, NM_001252024.2:c.4720dup:p.(Ser1574LysfsTer7), inherited from her mother, who did not have cataracts." (PMID 37511188, 2023). "Moreover, homozygous animal models for TRPM1 have also been described, showing incipient posterior cortical cataracts and immature cataracts." (PMID 37511188, 2023).
cervical cancer (1 paper, 2022). A primary or metastatic malignant neoplasm involving the cervix. "Furthermore, we analyzed the overall survival (OS) and disease specific survival (DSS) data of cervical cancer, and found that the overall survival prognosis of patients with low expression of TRPV1 showed worse prognosis, while patients with high expression of TRPM1 showed worse prognosis." (PMID 36072430, 2022).
ciliopathies (1 paper, 2021). "Based on the gene signature, we further investigated whether the overexpression of TRPM1 had any effects on the expression of genes linked to ciliopathies and photo-oxidative stress responses of photoreceptor cells, as well as whether the Ca2+ permeability of TRPM1 was required." (PMID 34301262, 2021).
Cognitive impairment (1 paper, 2023). Abnormal cognition is characterized by deficits in thinking, reasoning, or remembering. "Recently, a mice experiment proved the cognitive impairment observed in the 15q13.3 microdeletion syndrome phenotype, demonstrating that TRPM1 gene mutations may be associated with impaired cognitive function." (PMID 37107586, 2023).
deafness (1 paper, 2015). An inherited or acquired condition characterized by the complete loss of the ability to hear from one or both ears. "Across species, the genes identified with deafness or white pigmentation patterns include MITF, PMEL, KIT, EDNRB, CDH23, TYR, and TRPM1 in dog, cat, horse, cow, pig, sheep, ferret, mink, camelid, and rabbit." (PMID 26664958, 2015). "However, deafness does not appear to be associated with CSNB, and TRPM1 mutations have been associated with visual system disorders but not auditory disorders in other species." (PMID 26664958, 2015).
diabetic retinopathy (1 paper, 2012). "From this perspective, the identification of photoreceptor-specific changes in arrestin, Impg2, and Trpm1 raises the further possibility of a contribution by photoreceptors to diabetic retinopathy." (PMID 22605924, 2012).
glioma (1 paper, 2026). A benign or malignant brain and spinal cord tumor that arises from glial cells (astrocytes, oligodendrocytes, ependymal cells). "Potential glioma risk genes with a pathogenic GV most frequently played roles in cell adhesion (CTNND1, EPCAM), immune response (IFIH1, SAMHD1), and ion transport (SLC4A7, TRPM1)." (PMID 41546701, 2026).
lung disease (1 paper, 2025). "The remaining 11 genes in the region encode proteins associated with neurologic disorders (APBA2, CHRFAM7A, MTMR10, FAN1), skin and eye pigmentation or development (OCA2, HERC2, TJP1, TRPM1), nephritis (ARHGAP11B, MTMR10, FAN1), and lung disease (ENTREP2, NSMCE3)." (PMID 40013929, 2025).
skin cancer (1 paper, 2020). "For C20 (SKCM), the most representative gene is TRPM1 (regulated by 15q13.3), which is considered to be a metastasis-related important gene of skin cancer." (PMID 33166290, 2020).
Visual impairment (1 paper, 2024). "While ffERG b-wave amplitudes appeared maximally restored during June through August 2022, high levels of TRPM1 autoantibodies remained detectable in the patient’s serum during this same period, confirming that circulating TRPM1 autoantibodies alone are not sufficient to cause visual impairment." (PMID 39318594, 2024).
vitiligo (1 paper, 2016). Generalized well circumscribed patches of leukoderma that are generally distributed over symmetric body locations and is due to autoimmune destruction of melanocytes. "Lesional skin in patients with either localized or generalized vitiligo shows significantly reduced levels of TRPM1 mRNA expression." (PMID 27983625, 2016). "The contribution of TRPM1 to pigmentation might be relevant to the pathogenesis of human vitiligo." (PMID 27983625, 2016).
tumor (39 papers, 2010 to 2025). "In contrast to the potential tumor suppressor TRPM1, other members of this family have been implicated in oncogenic processes." (PMID 30248976, 2018). "However, in patients with acral melanoma, the increased TRPM1 expression was associated with shorter survival due to tumor progression." (PMID 36844925, 2022). "Similarly, a sequence in intron 8 of TRPM1 encodes the tumor suppressor miR-211 which is downregulated in aggressive tumor." (PMID 32324760, 2020). "The TRPM sub-family includes eight members, known as TRPM1-TRPM8, which were named based upon the first identified member, i.e., TRPM1, initially regarded as a tumor suppressor in melanoma." (PMID 40149710, 2025). "As described in this review, several miRNA/TRP channel pairs seem to play a key role in tumor biology such as TRPM1, TRPM3, and TRPM4." (PMID 36844925, 2022). "miR-211 is located on intron 6 of the Trpm1 gene at 15q13-q14, a locus that is frequently lost in many neoplasms." (PMID 32050841, 2020). "Of note, the expression of the TRPM1 gene is inversely correlated with aggressiveness of the cancer, implying a tumor suppressor gene." (PMID 32887395, 2020). "The microRNA miR-211 is localized on intron 6 of the Trpm1 gene at 15q13-q14, a locus that is frequently lost in neoplasms." (PMID 25889927, 2015). "TRPM1 has been suggested to be a tumor suppressor and a decrease in TRPM1 expression appears to be a prognostic marker for metastasis in patients with localized malignant melanoma." (PMID 24204345, 2013). "We cannot eliminate the formal possibility that the potential tumor suppressor activity of TRPM1 gene is, at least in part, due to the co-expression of miR-211 encoded from within its sixth intron." (PMID 21072171, 2010). "Cytological experiments suggest that TRPM1 might be a tumor suppressor because of the anti-tumor role of microRNA-211 which is located in TRPM1 gene." (PMID 31519770, 2019). "Based on these findings, we hypothesize that the ectopic expression of TRPM1 in tumor cells of some CAR and MAR patients may result in aberrant production of autoantibodies to TRPM1 through B-lymphocytic responses." (PMID 21611200, 2011). "It was speculated that TRPM1 is a tumor suppressor, hence the name “melastatin”." (PMID 32887395, 2020). "This led to the hypothesis of TRPM1 acting as a tumor suppressor (hence the name melastatin)." (PMID 30248976, 2018). "Specifically, TRPM1 and TRPM2 were upregulated in tumor tissues, whereas TRPM4, TRPM6, TRPM7, and TRPM8 were downregulated in the tumor group." (PMID 41562086, 2025). "We investigated the expression profile of TRPMs in the KIRC module of the TCGA database, and the heatmap indicated that among TRPM1-8, TRPM2 was significantly upregulated in the tumor samples." (PMID 36619219, 2023). "Administration of AUY922 markedly reduced the expression of TRPM1, AKT and phospho-AKT, and eliminated actively proliferating tumor cells." (PMID 34301262, 2021). "Recently, autoantibodies against TRPM1 were identified in patients with MAR, as well as in a few patients with other neoplasms." (PMID 32324760, 2020). "Targeting upstream regulators of TRPM1 expression, such as the transcription factor MITF, may represent an indirect yet effective strategy to enhance its tumor-suppressive effects." (PMID 40869148, 2025). "A very interesting recent study shed light to that issue and the authors report that tumor suppressive activity is not mediated by TRPM1 directly but by a microRNA (miR-211) hosted within an intron of TRPM1." (PMID 24204345, 2013).
tumor (continued). "In this context, the initially described tumor-suppressive and anti-invasive properties of TRPM1 have recently been shown to be executed by its intronic miR-211 (and not by TRPM1 itself) via down-regulation of the miR-211 direct and indirect targets TGFBR2, NFAT5, and IGF2R." (PMID 24039954, 2013). "However, subsequent studies have indicated that the tumor inhibitory function of TRPM1 might be mediated by miR-211 within its intron, rather than TRPM1 mRNA itself." (PMID 39633507, 2024). "However, we could not confirm whether TRPM1 is expressed in the tumor cells of the three PR patients examined in this study because tumor samples were not available." (PMID 21611200, 2011). "However, the molecular basis of the tumor suppressor activity of TRPM1 gene is not understood." (PMID 21072171, 2010). "MITF is also needed for miR-211 expression, suggesting that the tumor-suppressor activities of MITF and/or TRPM1 may at least partially be due to miR-211's negative post transcriptional effects on the KCNMA1 transcript." (PMID 21072171, 2010).
cancer (13 papers, 2013 to 2025). A tumor composed of atypical neoplastic, often pleomorphic cells that invade other tissues. "Then the correlation between TRPs and hazard ratio (HR) was detected, and found that the TRPV1 was negatively correlated with cancer risk; TRPM1 and TRPM4 were positively correlated with cancer risk." (PMID 36072430, 2022). "Among the members of the TRP families, the TRP vanilloid (TRPV) 6, TRPM1 and 8 channels are most commonly reported to be associated with malignant cell growth and cancer progression." (PMID 23426784, 2013). "Studies have demonstrated that some other TRP channels are highly expressed in cancer cells, and the amount of protein expresssion varies with the progression from normal to tumorigenic to metastatic cells, such as TRPM1, TRPM8, and TRPV6." (PMID 27023518, 2016). "The pathophysiological roles of TRPM1 have been identified in skin injury leading to cancer." (PMID 37445615, 2023).
retinopathy (8 papers, 2012 to 2025). "Trpm1 mutations cause pigmentation defects as well as retinal disorders known as complete congenital stationary night blindness in mammals." (PMID 36649236, 2023). "TRPM1 localization in ON-bipolar cells, and its implication in cCSNB when mutated, supports the conclusion that paraneoplastic retinopathies showing ON-bipolar cell dysfunctions are caused by autoantibodies binding TRPM1 and blocking its channel function." (PMID 32324760, 2020). "In order to understand how retinopathy may be caused by TRPM1 autoantibodies, retinal neurons were cultured in the presence of MAR serum." (PMID 23936334, 2013). "To validate the novel genetic testing tool for retinal disorders, we used four DNA samples from families, in which we had previously identified different types of mutations by Sanger sequencing: one 1 bp duplication and one 1 bp deletion in PRPF31 and missense mutations in TRPM1 and BEST1." (PMID 22277662, 2012). "Notably, we could also identify OTX2 binding sites on TRPM1 (+95286, +38, −140426, TSS), a transient receptor potential melastatin ion channel expressed in the RPE, the mutations of which have been reported in association with pigmentation defects and retinal disorders." (PMID 40565279, 2025).
eye disorder (1 paper, 2013). A non-neoplastic or neoplastic disorder that affects the eye. "We have identified a 1378 bp LTR insertion with the TRPM1 gene that is associated with both a pigmentation phenotype (LP) and an eye disorder (CSNB)." (PMID 24167615, 2013).
genetic disorder (1 paper, 2021). "The 15q13.3 microdeletion syndrome is a genetic disorder characterized by a wide spectrum of psychiatric disorders that is caused by the deletion of a region containing 7 genes on chromosome 15 (MTMR10, FAN1, TRPM1, MIR211, KLF13, OTUD7A, and CHRNA7)." (PMID 33785025, 2021).
lung (1 paper, 2011). "We performed Western blot analysis to identify an autoantibody against TRPM1 in the serum of a patient with lung CAR." (PMID 21611200, 2011).
TRPM1 also shares sentences with these, for which no sentence is quoted: schizophrenia (4 papers); Strabismus (3); amblyopia (2); bladder cancer (2); retinal degeneration (2); adenoma (1); age-related macular degeneration (1); Alzheimer disease (1); autism spectrum disorder (1); autosomal dominant polycystic kidney disease (1); breast carcinoma (1); channelopathies (1); colorectal cancer (1); cone-rod degeneration (1); coronary artery disease (1); cystic fibrosis (1); endometrial carcinoma (1); endothelial dysfunction (1); epilepsy (1); Exotropia (1); head and neck carcinoma (1); heart failure (1); Hypocalcemia (1); Hypomagnesemia (1); Intellectual disability (1); macular degeneration (1); metastatic disease (1); microdeletion syndrome (1); nephritis (1); neurologic disorders (1).
A further 10 diseases each share a sentence with TRPM1 in 1 paper.